YTHDC1 (YTH N6-methyladenosine RNA binding protein C1)
Diseases named in the same sentence as YTHDC1 in open-access papers (continued):
Sharing a sentence is not in itself a finding about the gene and the disease.
colorectal cancer (14 papers, 2021 to 2025). A primary or metastatic malignant neoplasm that affects the colon or rectum. "YTHDC1 silencing potently suppresses colorectal cancer cell proliferation by enhancing apoptotic cell death." (PMID 40986143, 2025). "For instance, YTHDC1-induced m6A modification of circNSUN2 promotes the liver metastasis of colorectal cancer via modulating cytoplasmic export." (PMID 39143552, 2024). "LINC00857 is upregulated and acts as an oncogene in colorectal cancer to promote colorectal cancer proliferation, migration and invasion by interacting with YTHDC1 and stabilizing SLC7A5." (PMID 35418193, 2022). "With respect to 'readers', both YTHDF1 and YTHDC1 were linked to higher GS, pathological T and pathological N. YTHDF1 is overexpressed in the colorectal cancer (CRC), and inhibition of Wnt/β-catenin pathway can be achieved by YTHDF1 silencing in CRC cells." (PMID 33995635, 2021). "For example, m6A-modified circNSUN2 can be exported from the nucleus to the cytoplasm by YTHDC1 in colorectal cancer, and circRNAs may undergo degradation by RNase L, miRNAs, and YTHDF2, etc., under certain conditions." (PMID 39075555, 2024). "In previous research, YTH domain-containing protein 1 (YTHDC1) mediated the nuclear output of circNSUN2 in a m6A methylation-dependent manner, thereby increasing cytoplasmic expression of circNSUN2 and promoting metastasis of colorectal cancer." (PMID 34922560, 2021). "Furthermore, YTHDC1 is increased in high-malignancy colorectal cancer tissues." (PMID 40986143, 2025). "YTHDC1 promoted the cytoplasmic output of methylated circNSUN2, regulates the stability of HMGA2, and promotes liver metastasis of colorectal cancer." (PMID 38978074, 2024). "Our co-immunoprecipitation and immunofluorescence cell staining assays confirmed that SLC12A5 directly bound to YTHDC1 in the nucleus of prostate cancer cells (the co-localization of SLC12A5 and YTHDC1 in the nucleus was also found in colorectal cancer cells)." (PMID 36609444, 2023). "Research has shown that YTH domain-containing protein 1 (YTHDC1) promotes the nuclear export of circNSUN2 which bind to m6A motifs, ultimately promoting colorectal cancer progression." (PMID 34888309, 2021). "Additionally, in colorectal cancer, WTAP activates the MAPK signaling pathway by mediating m6A methylation in VEGFA mRNA via YTHDC1, promoting tumor progression." (PMID 40316995, 2025). "Mechanistically, WTAP promotes VEGFA expression via a YTHDC1-dependent RNA splicing mechanism and activates the MAPK signaling cascade, which synergistically drives tumor angiogenesis and metastatic progression, underscoring its critical role in colorectal cancer oncogenesis." (PMID 40986143, 2025). "M6A-modified circNSUN2 binds YTHDC1 (YTH domain-containing protein 1) and promotes its exit from the nucleus, further binding IGF2BP2 (lnsulin-like growth factor 2 mRNA-binding protein 2), which stabilizes HMGA2 (high mobility group AT-hook 2) mRNA, thus promoting colorectal cancer liver metastasis." (PMID 38329551, 2024). "Interestingly, YTHDC1 ultimately combined with solute carrier family 7 member 5 (SLC7A5) and increased SLC7A5 mRNA stability to promote the proliferation and migration of colorectal cancer cells, implicating the critical role of LINC00857/YTHDC1/SLC7A5 axis in colorectal cancer progression." (PMID 37365581, 2023). "To further determine whether the interaction between endogenous SLC12A5 and YTHDC1 occurs in the cell nucleus, we conducted an immunofluorescence staining and found that endogenous SLC12A5 co-localized with YTHDC1 in the cell nucleus in SLC12A5 high-expressing prostate and colorectal cancer cells." (PMID 36609444, 2023).
breast cancer (13 papers, 2020 to 2025). A primary or metastatic malignant neoplasm involving the breast. "In breast cancer (BC), overexpression of YTHDC1 is associated with a poor prognosis." (PMID 40271153, 2025). "YTHDC1, an m6A reader, is detected to be highly expressed in various solid cancers, including breast cancer, esophageal cancer and hepatocellular carcinoma." (PMID 38745192, 2024). "In the future more researches were expected to comprehensively study the biological function of YTHDC1 in breast cancer to settle the controversy and further investigations on potential mechanisms were needed." (PMID 35501308, 2022). "Meanwhile, overexpression of YTHDC1 promoted the resistance to Adriamycin, indicating that YTHDC1 was an oncogene in breast cancer and induced DNA replication and DNA damage repair." (PMID 35501308, 2022). "Our work also shows that, rather than degradation of HOTAIR, m6A sites in HOTAIR mediate its high expression in breast cancer via YTHDC1." (PMID 36441764, 2022). "To test the role of YTHDC1 in HOTAIR’s ability to enhance breast cancer cell proliferation, we stably overexpressed or knocked down YTHDC1 in the context of WT or A783U HOTAIR overexpression in MDA-MB-231 cells." (PMID 36441764, 2022). "Furthermore, our work provides a rationale for the development of small molecule inhibitors targeting YTHDC1 as a therapeutic strategy to treat breast cancer and other cancers reliant on YTHDC1 such as AML, endometrial cancer, and glioblastoma." (PMID 35966596, 2022). "However, another study on breast cancer cells in vitro achieved the opposite result: YTHDC1 overexpression in MDA-MB-231 cells increased the cell viability and BRCA1/RAD51 expression level." (PMID 35501308, 2022). "To explore how breast cancer outcomes are affected by HOTAIR and YTHDC1 levels, we used Kaplan–Meier plotter." (PMID 36441764, 2022). "Among them, the expression of RBM15, VIRMA, HNRNPA2B1, and YTHDF1/2/3 were significantly upregulated, but METTL3, METTL14, METTL16, WTAP, FTO, YTHDC1, and EIF3A had lower expression in breast cancer compared to normal samples." (PMID 34804948, 2021). "EMP3 downregulates YTHDC1, a RNA-binding protein involved in m6a modification, which at least in part mediates the effects of EMP3 on breast cancer cells." (PMID 34511602, 2021). "With the increase of malignancy of breast cancer, the expression level of several m6A RNA methylation regulators, such as FTO, HNRNPA2B1 YTHDC1, IGF2BP1, IGF2BP2 and IGF2BP3, decreased or increased." (PMID 34141492, 2021). "In GSE70905, YTHDC1 (p < 0.05), IGFBP1 (p < 0.001), ALKBH5 (p < 0.001), WTAP (p < 0.001), YTHDF3 (p < 0.001) and HNRNPA2B1 (p < 0.001) were down-regulated in breast cancer to the adjacent." (PMID 33362863, 2020). "METTL3, METTL16, ZC3H13, YTHDC1 and FTO were expressed at a low level in breast cancer, while KIAA1429, RBM15, and YTHDF1 were expressed at a high level." (PMID 33362863, 2020). "YTHDC1 binds to m6A-modified EGF mRNA and promotes EGF synthesis, suggesting that METTL3 and YTHDC1 together enhance HR and cell survival during doxorubicin treatment, leading to the development of drug resistance in breast cancer." (PMID 37264402, 2023). "In addition, CPTAC data showed a significantly positive correlation between the protein expression levels of YTHDC1 and SMAD3 in breast cancer patient samples, which supports regulation of SMAD3 by YTHDC1." (PMID 35966596, 2022). "The negative modulation of YTHDC1 by EMP3 and the effect of YTHDC1 overexpression on breast cancer cells together demonstrate that YTHDC1 and m6A modification at least in part mediate EMP3-induced suppression of homologous recombination repair." (PMID 34511602, 2021).
lung carcinoma (12 papers, 2021 to 2025). "We demonstrate that LncPTEN1 splicing is promoted by the m6A reader protein YTHDC1, resulting in reduced LncPTEN1 expression in lung cancer cells." (PMID 40521243, 2025). "In this study, we demonstrate that YTHDC1 recognizes m6A modifications in PTEN pre-mRNA in lung cancer, and promotes LncPTEN1 expression through enhanced splicing." (PMID 40521243, 2025). "We reveal that YTHDC1 modulates the processing of LncPTEN1, resulting in its significantly decreased expression in lung cancer compared to normal tissues." (PMID 40521243, 2025). "As an m6A reader, YTHDC1 can stabilize or destabilize mRNAs by functioning as a RBP, and it has been implicated as a risk factor in lung cancer and acute respiratory distress syndrome." (PMID 37917328, 2024). "Here, we unveil that non-canonical activation of nuclear AURKA promotes an oncogenic RNA splicing of tumor suppressor RBM4 directed by m6A reader YTHDC1 in lung cancer." (PMID 35361747, 2022). "Downregulation of YTHDC1 promotes lung tumor progression and leads to ferroptosis resistance through m6A mediated upregulation of FSP1 protein levels, providing a treatment option for lung cancer with high YTHDC1 levels associated with ferroptosis." (PMID 38550378, 2024). "Moreover, YTHDC1 could modulate immune response in lung cancer, suggesting that YTHDC1 might have the potential for promoting the therapeutic efficacy of immune treatments." (PMID 35501308, 2022). "Together, our findings reveal that the m6A reader YTHDC1-directed RBM4 aberrant splicing is triggered by nuclear AURKA, providing novel opportunities for targeted therapy of lung cancer by blocking nuclear oncogenic signaling." (PMID 35361747, 2022). "Overall, our results elucidate a novel mechanism of how nuclear AURKA regulates m6A reader YTHDC1-mediated RBM4 aberrant splicing, and provide therapeutic opportunities for lung cancer by targeting nuclear translocation of AURKA." (PMID 35361747, 2022). "To evaluate the expression profile of m6A readers in lung cancer, we analyzed known readers, including YTHDF1/2/3, YTHDC1/2, HNRNPA2B1, HNRNPC/G, eIF3A, FMR1 and IGF2BP1/2, in LUAD and lung squamous cell carcinoma (LUSC) via the GEPIA database." (PMID 33232910, 2021). "The results showed that the expression profiles of eight m6A regulators (ALKBH5, FTO, HNRNPC, METTL14, RBM15, YTHDC1, YTHDC2, and ZC3H13) were significantly different among the three different lung cancer subtypes (P < 0.01)." (PMID 34805165, 2021). "To confirm this hypothesis, we first found a significant correlation between YTHDC1 and LINC00641 expression in lung cancer by using GEPIA database." (PMID 37311754, 2023).
prostate carcinoma (12 papers, 2019 to 2025). A carcinoma that arises from epithelial cells of the prostate gland. "As SLC12A5 is associated with the neuroendocrine differentiation of prostate cancer while YTHDC1 regulates gene expression in an m6A-dependent manner." (PMID 36609444, 2023). "YTHDC1 is a nuclear protein involved in splicing cancer-causing transcripts and plays a regulatory role in several cancers such as breast and prostate cancer." (PMID 35893234, 2022). "In prostate cancer, YTHDC1 regulates CD44 alternative splicing, which is associated with carcinogenesis." (PMID 32808488, 2020). "Here we report that SLC12A5 functions as an oncogene to promote tumor progression and castration resistance of prostate cancer through the N6-methyladenosine (m6A) reader YTHDC1 and the transcription factor HOXB13." (PMID 36609444, 2023). "Flag-SLC12A5 was able to bind with YTHDC1 in prostate cancer cells." (PMID 36609444, 2023). "Thus, HOXB13 is the target gene of SLC12A5/YTHDC1 complex in the nucleus that mediates the pro-tumor function of SLC12A5 in prostate cancer." (PMID 36609444, 2023). "In the present study, we demonstrated YTHDC1 could mediate the tumorigenesis and castration resistance promoting role of SLC12A5 by forming a SLC12A5-YTHDC1 complex in prostate cancer." (PMID 36609444, 2023). "Our data reveal SLC12A5 could bind with YTHDC1 to form a SLC12A5-YTHDC1 complex to regulate prostate cancer specific transcription factor HOXB13 in an m6A-dependent manner, uncovering a novel mechanism about how SLC12A5 promotes tumor progression." (PMID 36609444, 2023). "We found that HOXB13 mRNA was up-regulated in SLC12A5-overexpressing 22RV-1 cells and this upregulation was partially abrogated by knocking down YTHDC1 in the SLC12A5-overexpressing 22RV-1 cells, suggesting that HOXB13 was the target gene of SLC12A5/YTHDC1 complex in prostate cancer." (PMID 36609444, 2023). "We next determined whether YTHDC1 can mediate the SLC12A5’s oncogenic function in prostate cancer cells." (PMID 36609444, 2023). "Therefore, we first conducted a co-immunoprecipitation assay to verify whether SLC12A5 could interact with YTHDC1 in prostate cancer cells." (PMID 36609444, 2023). "YTHDC1 may participate in the RNA alternative splicing and affect the export of methylated mRNA from the nucleus to the cytoplasm, acting as the biomarker of prostate cancer and colon adenocarcinoma." (PMID 35620523, 2022). "YTHDC1 can form a complex with SLC12A5 to upregulate HOXB13, leading to the promotion of prostate cancer progression." (PMID 40221424, 2025). "Mechanistically, SLC12A5 interacts with the m6A reader YTHDC1 in the nucleus and in turn upregulates the transcription factor HOXB13 to promote the tumor progression of prostate cancer." (PMID 36609444, 2023). "Taken together, these results indicated that SLC12A5 interacted with YTHDC1 to form a SLC12A5-YTHDC1 complex in the cell nucleus, thus mediated the progression of prostate cancer." (PMID 36609444, 2023). "Furthermore, expression of YTHDC1, especially its alternative splicing components, was detected in a panel of prostate cell lines that was absent in benign cell lines, indicating that YTHDC1 might act as an oncogene in prostate cancer." (PMID 35806168, 2022). "Subsequently, we determined CBLL1, FTO, YTHDC1, HNRNPA2B1 as crucial m6A regulators of prostate cancer." (PMID 34899855, 2021). "Using a yeast two-hybrid assay and immunoprecipitation we show that metadherin interacts with YTHDC1, Sam68 and T-STAR and demonstrate that T-STAR is significantly overexpressed in prostate cancer tissue compared to benign prostate tissue." (PMID 31450747, 2019). "As we saw altered expression of T-STAR in prostate cancer, we used a panel of prostate cell lines to examine the protein expression of alternative splicing components, specifically Sam68, T-STAR, YTHDC1 and metadherin." (PMID 31450747, 2019).
prostate carcinoma (continued). "Interestingly, SLC12A5 was detected in the cell nucleus and formed a complex with nuclear m6A reader YTHDC1, which in turn upregulated HOXB13 to promote the prostate cancer progression." (PMID 36609444, 2023). "We selected 12 genes, which have been demonstrated to be required for the enzalutamide resistance and neuroendocrine differentiation of prostate cancer, and determined whether their expression are affected by the SLC12A5/YTHDC1 complex." (PMID 36609444, 2023). "The expression of YTHDC1 has been detected in a panel of prostate cell lines and not in the benign prostate cell lines, indicating that YTHDC1 may function as an oncogene in prostate cancer." (PMID 34897032, 2021).
leukemia (11 papers, 2022 to 2025). A malignant (clonal) hematologic disorder, involving hematopoietic stem cells and characterized by the presence of primitive or atypical myeloid or lymphoid cells in the bone marrow and the blood. "Conversely, the loss of Ythdc1 inhibits DNA synthesis in leukemia stem cells (LSCs)." (PMID 39414764, 2024). "Over-expression of either YTHDC1 or HOXB-AS3 can amplify the proliferation of leukemia stem cells (LSCs), and impair their apoptosis." (PMID 39342406, 2024). "The modification allows YTHDC1 to form biomolecular condensates called YACs (YTHDC1-m6A condensates), which are increased in leukemia cells." (PMID 35406602, 2022). "Similarly, YTHDC1 maintains the stemness of leukemia stem cells and accelerates their self-renewal efficiency." (PMID 39090090, 2024). "Furthermore, the dysregulation of YTHDC1, an m6A reader protein, has been implicated in the pathogenesis of AML and in the maintenance of leukemia stem cells (LSCs)." (PMID 39414764, 2024). "A possible mechanism could be via stabilized phase-separated nuclear bodies analogous to nuclear YTHDC1-m6A condensates in leukemia." (PMID 36441764, 2022). "In AML, this RBFOX2/m6A/RBM15/YTHDC1/PRC2 axis is essential for leukemia cell survival, proliferation, and the self-renewal and maintenance of leukemia stem/progenitor cells." (PMID 41403702, 2025). "They proved that the formation of nuclear YTHDC1-m6A condensates (nYACs) mediated by LLPS enables YTHDC1 to protect some mRNAs, such as MYC mRNA, from being degraded by PAXT complex and exosome, thus facilitates the process of leukemia." (PMID 35999621, 2022). "Similar to YTHDF1, while not significant for hematopoiesis development, YTHDC1 has also been unequivocally demonstrated to be indispensable for AML cell survival, differentiation, and leukemogenesis, advancing the progression of leukemia through various mechanisms." (PMID 39342406, 2024).
hepatocellular carcinoma (10 papers, 2020 to 2025). A malignant tumor that arises from hepatocytes. "Hepatocyte‐specific deletion of Ythdc1 impairs hepatocyte maturation, causing liver injury, contributing to nonalcoholic steatohepatitis and hepatocellular carcinoma." (PMID 40536447, 2025). "DUSP4 suppresses ferroptosis in hepatocellular carcinoma by regulating ferritin mRNA localization through YTHDC1 phosphorylation, contributing to sorafenib resistance." (PMID 39315094, 2024). "Further analysis showed that the higher expression of YTHDC1 was statistically related to the poorer survival of hepatocellular carcinoma patients." (PMID 35501308, 2022). "Recent studies have demonstrated that YTHDC1 facilitates cytoplasmic delivery of circMET in renal cell carcinoma, as well as the cytoplasmic translocation of circHPS5 in hepatocellular carcinoma (HCC) in an m6A-dependent manner." (PMID 36446779, 2022). "In another study concerning hepatocellular carcinoma, YTHDC1 favored the cytoplasmic export of m6A modified circHPS5 which acted as a miR-370 sponge to downregulate the expression of HMGA2 and thus accelerate the hepatocellular carcinoma tumorigenesis." (PMID 35501308, 2022). "Here, 13 differentially expressed m6A methylation regulators were confirmed in 374 hepatocellular carcinoma (HCC) patients, among which RBM15, YTHDC1, YTHDF1, and YTHDF2 were significantly variant in different stages and grades." (PMID 32974160, 2020). "Reportedly, in hepatocellular carcinoma (HCC), YTHDC1 helps m6A-modified circHPS5 to exit the nucleus, increasing the number of HCC stem cell spheres and upregulating the expression of stem cell marker CD133." (PMID 39090090, 2024). "Dual-specificity phosphatase 4 (DUSP4) inhibits sorafenib-induced ferroptosis in hepatocellular carcinoma by activating the RNA m6A reader, YTH N6-methyladenosine RNA binding protein C1 (YTHDC1), leading to enhanced expression of FTH and FTL." (PMID 39624080, 2024).